ABCB1 (ATP binding cassette subfamily B member 1)
Diseases named in the same sentence as ABCB1 in open-access papers (continued):
Sharing a sentence is not in itself a finding about the gene and the disease.
tumor (continued). "The MDR phenotype transferred by EVs protected sensitive tumor cells for up to 4 months, facilitating the development of intrinsic ABCB1-mediated resistance." (PMID 39403600, 2024). "Overexpression of ABCB1 can mediate paclitaxel resistance in different tumor types, including colorectal, lung, ovarian and breast." (PMID 38163893, 2024). "Our results also demonstrate that DOX-induced labile Zn2+ increases ABCB1 to help tumor cell to evade the cytotoxic effects of DOX." (PMID 39507258, 2024). "Tempol and YC-1 inhibit tumor growth by blocking ROS production and the induction of ABCB1, respectively." (PMID 38893207, 2024). "Both as a tumor cell resistance and stem cell indicator, ABCB1 is positively correlated with poor prognosis." (PMID 39507258, 2024). "The ABCB1 gene was also found to be upregulated in untreated tumours of various types, in human multidrug-resistant cells, and in cells selected with different drugs." (PMID 38674115, 2024). "After protein and/or mRNA expression of ABCC1 and ABCB1 was established, the effects on pumps were examined by measuring ABCB1/ABCC1‐mediated calcein AM efflux in 2D‐cultured SK‐N‐AS cells to isolate the effect on tumor cells only." (PMID 37519014, 2024). "Surface ABCB1 expression was also highly upregulated in an POBNCI_ACC004 resistant compared to an untreated POBNCI_ACC004 control tumor." (PMID 39416174, 2024). "This study also demonstrated that the functional transfer of ABCB1 occurred across different tumor cell types, suggesting a broad mechanism for the dissemination of MDR." (PMID 39403600, 2024). "The up-regulation of ABCB1 in the tumor cell population of the cluster group with longer PFS at the six-week timepoint compared to the initial timepoint supports previous research implicating ABCB1 in acquired multi-drug resistance and relapse in cL." (PMID 39591314, 2024). "To evaluate the therapeutic potential of αCD7/EVs/CytC/siBcl2 in chemotherapy‐resistant tumours, we established chemotherapy‐resistant Molt‐4 cells (CR‐Molt‐4 cells) by transfecting an ABCB1‐expressing lentivirus." (PMID 39676736, 2024). "Here, we found that zosuquidar, a ABCB1 inhibitor, significantly promoted PD‐L1 degradation, thus inducing the infiltration of cytotoxic T cell and repressing tumor growth in CT26 and humanized xenograft mouse model." (PMID 39229920, 2024). "Taken together, these results indicated that zosuquidar mediated PD‐L1 degradation and tumor growth inhibition were extremely dependent on the expression of ABCB1." (PMID 39229920, 2024). "The ABCB1 protein is known for its involvement in multidrug resistance of tumor cells by preventing intracellular accumulation of cytotoxic drugs." (PMID 37367074, 2023). "The transport of the rapalogues out of the tumors is influenced by both the amount of ABCB1 in the tumor cells and possibly by other drugs taken by the patient that are also transported out of cells by ABCB1." (PMID 37240915, 2023). "Among the pumps found in tumor stem-like cells, ABCB1, Multidrug Resistance 1 (MDR1), ABCC1, Multidrug Resistance Protein 1 (MRP1), and ABCG2, Breast cancer-resistance protein 1 (BCRP1) are the most well-known." (PMID 38002496, 2023). "IL-8 also induces chemoresistance in tumor cells by upregulating the ATP-binding cassette subfamily B member 1 (ABCB1), which leads to the production of multidrug resistance protein 1 (MDR1), a protein linked with drug resistance." (PMID 37849764, 2023). "The results show that hydrophobic statins administered with docetaxel increase the accumulation of the drug in the tumor cell a.o. by blocking the ABCB1 channel." (PMID 38136555, 2023). "The ICG intensity clearly correlated with the expression levels of iNOS, leading to an increase in nitric oxide concentration in tumor cells, which was related with the down-regulation of ABCB1 expression." (PMID 37228164, 2023).
tumor (continued). "Considering ABCB1 relevance during tumor progression, in contrast to previous findings correlating ABCB1 upregulation with enhanced resistance to chemotherapy, we did not observe any alteration on its activity after TGF-β-induced EMT." (PMID 37047018, 2023). "For now, it is important to incorporate what is currently known about CYP3A4, CYP3A5, CYP2C8, and ABCB1 into the assessment of a patient when the mTOR pathway is a desired target in treating a tumor." (PMID 37240915, 2023). "Overexpression of ABCB1 has been demonstrated in tumor samples obtained from patients whose tumors have developed resistance to the ALK inhibitor ceritinib in the absence of secondary ALK mutations." (PMID 37840856, 2023). "In tumor cells and at the blood-brain barrier, ABCB1 and ABCG2 restrict the uptake of anticancer drugs, and transporter expression levels were thought to correlate with the extent of multidrug resistance." (PMID 36973040, 2023). "On the basis of the mechanism of the ABCB1 ‘hydrophobicity vacuum cleaner’ model, lipid solubility is the key factor to improve the reverse tumor MDR activity." (PMID 37233508, 2023). "ABCB1 protein levels were demonstrated to be reduced after A1BG-AS1 silencing in mouse tumor tissues." (PMID 38007504, 2023). "Since ABCB1 is often expressed in tumor cells and in tumor stem cells, it contributes to the chemotherapy resistance of tumors, referred as multidrug resistance." (PMID 37511101, 2023). "The antibodies MRK16 and MRK17 inhibited Abcb1-mediated efflux in vitro and in animal tumor models and increased doxorubicin efficacy." (PMID 36973040, 2023). "In uroepithelial carcinoma, chemotherapy induces the expression of IL-8 in tumor cells, subsequently upregulating the expression of ABCB-1 in endothelial cells, leading to tumor drug resistance." (PMID 38069225, 2023). "Among them, the marine alkaloids Ningalin B-1 and Naamidine-1 have preferable ABCB1 regulatory activity and reversed the tumor MDR." (PMID 37233508, 2023). "In conclusion, these results suggest enhancement of the efficacy of the chemotherapeutic drug doxorubicin by AIF-1, laying the basis for the future development of new ABCB1 inhibitors for tumor treatment." (PMID 36674503, 2023). "Upregulation of transmembrane transporters such as ATP-binding cassette subfamily B member 1 (ABCB1 or P-glycoprotein) in tumor cells contributes to drug resistance." (PMID 37367074, 2023). "The human body contains 48 ABC transporters, with ABCB1, ABCC1, and ABCG2 being closely associated with tumor MDR." (PMID 38067428, 2023). "In this article, we show that gemcitabine upregulates ABCB1 while dFdCTP, an active metabolite of gemcitabine, is the main substrate of ABCB1 and can be expelled from tumor cells." (PMID 35463361, 2022). "More importantly, several ABC transporters have been frequently found to be overexpressed in a variety of tumor resistant cells, such as P-glycoprotein (P-gp, ABCB1) and breast cancer resistance protein (BCRP, ABCG2)." (PMID 36120340, 2022). "Consistently, ABCB1 expression was significantly higher in the tumour cells from Zip1+/+ mice than in those from Zip1−/− mice." (PMID 36207295, 2022). "MiR-214-3p, for example, serves as a tumor suppressor by targeting ABCB1 and XIAP proteins, preventing multi-drug resistance and stimulating apoptosis." (PMID 35322101, 2022). "In the field of oncology, some literature had found that WNT/β-catenin canonical signaling pathway positively regulates the ABCB1 gene expression in tumor cells." (PMID 36248871, 2022). "This was because MEK contributes to increased expression of ABCB1, a drug efflux transporter that releases PpIX from tumor cells, and to the activity of ferrochelatase, which converts PpIX to heme." (PMID 35203195, 2022). "To investigate the mechanism by which A011 reversed drug resistance in tumor cells, we determined the effect of A011 on the function of ABCB1 and ABCG2 transporters." (PMID 36120340, 2022).
tumor (continued). "In this study, we show that MG53 inhibits proliferation of sensitive SW620 and doxorubicin-resistant and ABCB1 overexpressing SW620/AD300 cells and reduces tumor growth and progression in ABCB1 mouse xenograft models." (PMID 36147477, 2022). "Highly expressed IGF2BP3 can directly bind to the m6A-modified region of target mRNA, thereby promoting the stability and expression of specific genes, such as TMBIM6, VEGF, and ABCB1, leading to tumor progression, angiogenesis, and chemoresistance." (PMID 35136045, 2022). "Together with the Rab-coupling protein, this tumor suppressor was reported to facilitate ABCB1 reconstitution to the plasma membrane, thereby increasing cisplatin efflux." (PMID 35205642, 2022). "Transferring multidrug resistance- (MDR-) associated proteins such as P-glycoprotein (P-gp), a glycoprotein encoded by ABCB1 gene, by TD exosomes to target cells is another mechanism in chemotherapeutic resistance in tumor cells." (PMID 36117723, 2022). "Co-culture of LLC-GFP-luc cells with mCAF-induced ABCB1 expression in tumour cells, which was reduced by heptanol or TPEN pretreatment." (PMID 36207295, 2022). "Lapatinib is also found to be able to bind to ABCB1 competitively, increasing gemcitabine efficacy by blocking the efflux of dFdCTP from tumor cells, and promoting its accumulation within cells." (PMID 35463361, 2022). "Our results demonstrated pharmacological inhibition of USP7, which further downregulated ABCB1 expression, suppressed tumor growth, and considerably restored the effectiveness of doxorubicin and paclitaxel." (PMID 36291159, 2022). "The P-glycoprotein belongs to the ATP-binding cassette superfamily and was first described in tumor cells resistant to anticancer agents as a result of ABCB1 overexpression." (PMID 36037240, 2022). "We then estimated chemotherapy-associated drug-resistant genes, including ABCB1, ABCC1 and ABCG2, and found that curcumol significantly reversed the mRNA levels of CDDP-induced ABCB1, ABCC1 and ABCG2 genes in the tumor tissue." (PMID 35889217, 2022). "We analyzed the relative expression of ABC-transporters’ genes ABCB1, ABCC1, and ABCG2, transcription factor YB-1 and MVP gene associated with the distribution of xenobiotics in cytoplasm, in 70 tumor samples." (PMID 35328603, 2022). "The sensitive and drug resistant cell lines were inoculated into the flank region of mice to generate the parental and ABCB1 overexpressing tumor xenograft model, respectively." (PMID 36147477, 2022). "Inhibition of AKT with LY294002 effectively inhibited the upregulation of ABCB1 by Zn2+ stimulation in tumour cells, suggesting an AKT-dependent pathway." (PMID 36207295, 2022). "To further validate that ZIP1+ fibroblast-dependent upregulation of the multidrug resistance protein ABCB1 expression in tumour cells contributed to chemoresistance, we used paclitaxel combined with doxycycline to treat the co-injected tumours." (PMID 36207295, 2022). "Correspondingly, Zip1+/+ MEFs reduced DOX and increased the expression of ABCB1 in tumour cells treated with DOX for 4 h." (PMID 36207295, 2022). "The MDR reversal by MRTX849 in vivo was investigated in two ABCB1-overexpressing tumor xenograft models in nude mice." (PMID 36104708, 2022). "Some studies have proposed that expression of ABCB1 messenger RNA correlates with tumor severity intrinsic to drug resistance after chemotherapy." (PMID 35163649, 2022). "ATP binding cassette subfamily B member 1 (ABCB1) is an efflux drug transport protein located in the cell membrane that is responsible for excreting drugs from tumor cells, resulting in multidrug resistance." (PMID 35659268, 2022). "In tumor specimens of colorectal cancer patients who survived for 5 years, the expression level of ABCB1 was positively correlated with the expression levels of Beclin1, LC3, Rictor, and negatively correlated with the expression level of Raptor." (PMID 35136409, 2022).
tumor (continued). "Knockdown of FTH1P3 decreases the 50% inhibitory concentration value of paclitaxel, induces cell cycle arrest at the G2/M phase, and suppresses tumor growth of paclitaxel-resistant BC cells as well as ABCB1 protein expression in vivo." (PMID 34947885, 2021). "The ABCB1 gene encodes one of the major ATP-binding cassette (ABC) drug transporters, known for increasing drug efflux from tumor cells." (PMID 34439209, 2021). "In treating with the chemotherapeutic drugs, amplification of the ABCB1-related amplicon region containing SRI was sufficient to drive tumor chemoresistance." (PMID 34869449, 2021). "Increased tumor IL-8 secretion promoting TECs express high levels of a drug efflux transporter, ABCB1." (PMID 34095111, 2021). "In the meantime, ibrutinib can also reduce the drug resistance of tumor cells to paclitaxel by inhibiting the outflow function of the ATP-binding cassette subfamily B member 1 (ABC B1/P-glycoprotein) and subfamily C member 10 (ABCC 10/MRP 7)." (PMID 34976824, 2021). "Fluoxetine inhibits tumor multidrug resistance by regulating the expressions of P-glycoprotein (P-gp), ABCB1 (MRP1), and glutathione S-transferase-pi (GST-π), which sensitizes tumors to chemotherapy." (PMID 34006301, 2021). "Of these samples, ULP-WGS identified a total of 68 with sufficient tumor purity (>7%) to confidently detect ABCB1 amplification and other CNAs." (PMID 34439209, 2021). "Changes in paclitaxel exposure and expression of ABCB1 (P-glycoprotein) over time were studied in both tumor tissue and normal appearing esophageal mucosa." (PMID 34858183, 2021). "While immortalized cell lines are considered poor clinical surrogates due to their relative homogeneity, we identified elevated ABCB1 expression in clinically relevant, paclitaxel-resistant tumor organoid models, as well." (PMID 34347777, 2021). "ABCB4 (also known as MDR3) is closely related to ABCB1 (78% identity), and like ABCB1, can act as a drug efflux pump contributing to tumor drug resistance." (PMID 34597626, 2021). "In general, in the primary tumours, the ABCB1 was the dominant transporter and the expression levels of ABCG2 was markedly lower." (PMID 34065402, 2021). "In line with the results seen during the first cycle, the expression of ABCB1 during the last cycle was also significantly higher in tumor samples compared to healthy esophageal tissue (p = 0.01)." (PMID 34858183, 2021). "Another study demonstrated the specific inhibition of MDR1/ABCB1, which restored the potency of Dox and vinblastine in ABCB1-expressing NCI/ADR (Res) cells, a drug-resistant variant of MCF7 cells, in a tumor spheroid model." (PMID 34208283, 2021). "The effects of ABCB1 knockout on drug resistance phenotype, intracellular drug accumulation, and tumor spheroid morphology were investigated." (PMID 34977876, 2021). "Nine tumor samples were evaluable for immunohistochemistry at the last cycle: the 8 evaluable adenocarcinoma samples all remained strongly positive for ABCB1." (PMID 34858183, 2021). "In vivo studies demonstrated that inhibition or induction of ABCB1 in multidrug resistant tumor cells influences the intratumoral paclitaxel exposure." (PMID 34858183, 2021). "We have reported that A375SM-derived tumor CM induced resistance to paclitaxel by upregulating MDR-1/ABCB1 in human NEC:HMVEC18." (PMID 34226586, 2021). "ABCB1 plays a significant role in pumping external molecules through ATP hydrolysis that reduces the chemosensitivity of tumor cells." (PMID 34425750, 2021). "Do these pathways regulate directed cell movement within the tumor and does ABCB1 contribute to this potential mechanism?" (PMID 35582031, 2021). "The morphology of tumor spheroid also reflected the restored drug sensitivity mediated by ABCB1‐targeting CRISPR/Cas9 gene editing." (PMID 34977876, 2021).
tumor (continued). "We have recently published a novel mechanism of ETV7-mediated resistance to the chemotherapeutic agent Doxorubicin which involves the downregulation of DNAJC15 tumor suppressor leading to an increased expression of ABCB1 efflux pump." (PMID 34315857, 2021). "One of the first studies to establish a link between ABC transporters and tumorigenesis was by Mochida and coworkers, who established that the loss of P-glycoprotein (ABCB1, P-gp) suppresses intestinal polyp formation and hampers tumor progression in mice." (PMID 32587767, 2020). "In no case were our selected myocardial l-Type calcium channel modulators 6 and 7 able to significantly inhibit the proliferation of tumor cells, and they did nothing to hamper the ABCB1 activity at low equitoxic concentration." (PMID 32120861, 2020). "These analyses showed that ABCB1 was upregulated in BV-treated tumours, with expression detected in both 1 mg/kg and 3 mg/kg BV-treated tumours, but undetectable in vehicle-control-treated tumours." (PMID 32684628, 2020). "Multidrug resistance can be caused by ATP-binding cassette (ABC) transporters, e.g., by higher efflux of drugs out of tumor cells by P-glycoprotein (Multidrug resistance, MDR coded by ABCB1 gene)." (PMID 33334016, 2020). "The 175 kDa P-glycoprotein (P-gp) is the ATP-binding cassette (ABC) subfamily B member 1 (ABCB1) efflux transporter that was first identified in tumor cells showing resistance to a wide range of chemotherapeutic drugs, including MTX." (PMID 32872504, 2020). "Parental (SW620) and ABCB1-overexpressing drug-resistant (SW620/AD300) cells were implanted into athymic nude mice to create the ABCB1-overexpressing tumor xenograft model." (PMID 32098067, 2020). "In tumor tissues, the methylation status of the ABCB1 promoter was inversely correlated with ABCB1 expression." (PMID 33066132, 2020). "A tumor xenograft of the ABCB1 knockdown cells showed inhibited tumor expansion compared to the control." (PMID 32587767, 2020). "This makes ABCB1 an interesting target for the enhancement of tumor therapy, and ABCB1 inhibitor candidates have been shown to dramatically increase the potency of chemotherapeutics in vitro." (PMID 32056006, 2020). "As previously reported, we established ABCB1- or ABCG2-overexpressing tumor xenograft models, with a slight modification." (PMID 32098067, 2020). "There was no significant change in the body weight of the animals in the ABCB1 tumor xenograft models." (PMID 32098067, 2020). "Drug efflux pump ABCB1 is overexpressed in chemoresistant neoplasms where it effluxes various chemotherapeutic agents from cells." (PMID 32020017, 2020). "Sorcin is “resistance-related” because its gene and ABCB1 are often co-amplified in MD-resistant tumor cells." (PMID 32268494, 2020). "The ABCB1 promoter was significantly higher methylated in tumors than in tumor-adjacent and tumor-distant tissues from the same patients and normal breast tissues of the control group, suggesting a role of ABCB1 promoter methylation in breast carcinogenesis." (PMID 33066132, 2020). "The ATP binding cassette (ABC) superfamily transporters (e.g. ABCG2 and ABCB1) were found to extrude PS out of the tumor cells." (PMID 33552982, 2020). "Upon reaching the tumor cells, chemotherapeutic drugs first bind to ABCB1, then ATP hydrolysis generates energy for pumping the drugs out of the cells, decreasing the concentration of intracellular drugs, and therefore leading to drug resistance." (PMID 32793491, 2020). "Penetration of the human blood–brain barrier by AZD1775 is facilitated by uptake into the CNS through the OATP1A2 transporter and limited transporter-mediated efflux by ABCB1/ABCG2 in the relatively acidic tumor microenvironment." (PMID 32204315, 2020). "A significant reduction in tumor volume and weight occurred in the parental and ABCB1- or ABCG2-overexpressing tumors, compared to the single treatment groups." (PMID 32098067, 2020).